AMH (anti-Mullerian hormone)
Diseases named in the same sentence as AMH in open-access papers (continued):
Sharing a sentence is not in itself a finding about the gene and the disease.
polycystic ovary syndrome (continued). "Another correlation is demonstrated in this study of AMH with polycystic ovarian syndrome (PCOS)." (PMID 35761734, 2014). "However, the mean level of AMH was highest in the phenotypes of anovulation, polycystic ovaries and hyperandrogenism (11.1 ng/ml)." (PMID 25119192, 2014). "This increase is due to increased synthesis and secretion of AMH by polycystic ovaries." (PMID 25119192, 2014). "Plasma AMH and inhibin B concentrations were measured in the 4 more recent cases because granulosa cell tumors may secrete these hormones and AMH is increased in prepubertal daughters of women with polycystic ovary syndrome." (PMID 20593028, 2010). "More than 20 years ago, significantly increased AMH levels were found in women with polycystic ovary syndrome (PCOS), and were suggested as a surrogate marker for polycystic ovaries." (PMID 41515619, 2026). "On the contrary, AMH and luteinizing hormone (LH) levels are high in patients affected by polycystic ovary syndrome (PCOS)." (PMID 40875133, 2025). "In polycystic ovary syndrome (PCOS), AMH levels are significantly higher due to an increased number of granulosa cells (GCs) and enhanced transcriptional activity mediated by Foxl2, Sox9, and Gata4." (PMID 40724853, 2025). "In parallel, anti-Müllerian hormone (AMH) reflects ovarian reserve and remains relatively stable across the cycle, while testosterone, although often overlooked, plays a key role in folliculogenesis and is central to disorders like polycystic ovary syndrome (PCOS)." (PMID 40895285, 2025). "An inverse relationship was reported between body mass index (BMI) and AMH levels, especially in patients with insulin-resistance and polycystic ovary syndrome (PCOS)." (PMID 39336427, 2024). "Women with polycystic ovary syndrome (PCOS) have high circulating anti-Müllerian hormone (AMH) levels which is correlated with antral follicle count and polycystic ovarian morphology and negatively correlated with body mass index (BMI)." (PMID 36309748, 2022). "After MET treatment, the serum AMH decreased in polycystic ovary syndrome (PCOS) patients (WMD = -1.79, 95% CI: -2.32 to -1.26, P < 0.00001), in both obese and non-obese patients." (PMID 35698127, 2022). "AMH serum levels are closely related to the numberof primary antral follicles in healthy women and thosewith polycystic ovary syndrome (PCOS)." (PMID 33687164, 2021). "The AMH level is used to assess ovarian reserve, to predict ovarian response for in vitro fertilization, to assess damage to the ovary by surgery or chemotherapy, to predict the reproductive life span, to evaluate polycystic ovarian syndrome, and to diagnose premature ovarian insufficiency." (PMID 32656076, 2020). "Elevated levels of AMH are observed also in patients with polycystic ovary syndrome (PCOS), where they are elevated up to 2–12 times." (PMID 30884769, 2019). "We intended to establish the threshold for anti-Mullerian hormone (AMH) in the diagnosis of polycystic ovary syndrome (PCOS) in China." (PMID 30153296, 2018). "In women with polycystic ovary syndrome (PCOS), supplementation has shown benefits such as reduced AMH and a possible anti-inflammatory effect, although its impact on pregnancy rates after IVF remains uncertain." (PMID 41301826, 2025). "These criteria encompass three components: polycystic ovary morphology or elevated anti-Müllerian hormone (AMH), hyperandrogenemia or clinical androgenization, and irregular cycles." (PMID 40861693, 2025). "It has shown clinical utility in predicting the success of in-vitro fertilization, diagnosis of polycystic ovary syndrome (PCOS) and premature ovarian failure (POF); elevated AMH level is a hallmark of PCOS, while decreased levels are a sensitive indicator of POF." (PMID 41196903, 2025).
polycystic ovary syndrome (continued). "A potential explanation for these unexpected late recoveries could be the presence of polycystic ovary syndrome (PCOS) in these individuals, because they have AMH values far above the 90th percentile for their age suggesting polycystic ovary morphology (PCOM)." (PMID 40848466, 2025). "We used a random-effects model to estimate the pooled correlations between AMH and the homeostatic model assessment for insulin resistance (HOMA-IR) in patients with polycystic ovarian syndrome (PCOS)." (PMID 38762718, 2024). "Although a causal relationship between AMH and testosterone has not been established, it has been suggested that testosterone could affect follicular growth, and that AMH might induce gestational hyperandrogenemia." (PMID 38397936, 2024). "This clinical trial was designed and conducted due to the anti-inflammatory potential of Oleoylethanolamide (OEA) to examine the effect of OEA supplement on glycemic status, oxidative stress, inflammatory factors, and anti-Mullerian hormone (AMH) in women with polycystic ovary syndrome (PCOS)." (PMID 38778429, 2024). "Clinical studies have shown that vitamin D supplementation can lower androgen levels, lower anti-Mullerian hormone (AMH) levels, normalize the metabolic profile, and regularize periods in women with polycystic ovarian syndrome (PCOS)." (PMID 36771395, 2023). "To analyze whether metformin treatment in patients with polycystic ovary syndrome (PCOS) results in a decrease of anti-Müllerian hormone (AMH) levels, we reviewed and analyzed PCOS studies which evaluated serum AMH levels before and after metformin treatment." (PMID 37381009, 2023). "Predicting ovarian response to COS is currently based on different factors, such asage, serum FSH, serum anti-Müllerian hormone (AMH), basal antral folliclecount (AFC), and presence of polycystic ovarian syndrome (PCOS)." (PMID 36952624, 2023). "AMH supplementation is able to maintain follicular reserve in some ovarian injury models, such as chemotherapy-induced premature ovarian failure, polycystic ovary syndrome (PCOS)." (PMID 36926197, 2023). "Further possible mechanisms are the decrease in anti-Müllerian hormone (AMH) concentrations and the production of “holes” in the very thick cortical wall of the polycystic ovary." (PMID 36013469, 2022). "We have analyzed literature facts about effects of bariatric surgery on the function of the hypothalamic-pituitary-ovarian axis, polycystic ovary syndrome (PCOS), anti-Mullerian hormone (AMH) and sexual dysfunction in obesity and pregnancy in obesity." (PMID 34878586, 2022). "However, in women with polycystic ovary syndrome (PCOS), serum AMH was observed to correlate negatively with BMI." (PMID 35937797, 2022). "Young age, long menstrual cycles, polycystic ovary syndrome (PCOS), and hyper response in a previous cycle are suggestive of high ovarian reserve, but the stronger predictors of hyper response are AMH and AFC." (PMID 28890430, 2017). "The study demonstrated that a generally linear decreasing pattern was found for AMH with age in the 75th percentile and below, whereas a slight biphasic pattern was observed in the 90th and 97th percentiles which could be due to the inclusion of women with polycystic ovarian syndrome." (PMID 29240820, 2017). "Women with polycystic ovarian syndrome (PCOS) have elevated circulating and intrafollicular AMH levels." (PMID 28913122, 2016). "Several studies have suggested that AMH serum levels may be a marker for polycystic ovary syndrome (PCOS)." (PMID 25119192, 2014). "The aim of the present study was to evaluate in patients with polycystic ovary syndrome (PCOS) whether metformin administration affects serum and follicular AMH levels, and whether this is related to ovarian response to the treatment." (PMID 20663178, 2010). "Anti-Müllerian hormone (AMH) measured in adolescence as biomarker for prediction of adult polycystic ovary syndrome (PCOS) is doubtful but not substantiated." (PMID 33351079, 2021).
polycystic ovary syndrome (continued). "In PCOS, the polycystic ovarian morphology is a sine qua non of high antral follicle repertoire, and aligned with this, serum levels of AMH are higher in women with PCOS compared to those without polycystic ovaries." (PMID 34063169, 2021). "In addition AMH levels are related to the severity of PCOS, and a positive link between AMH concentration and severity of hyperandrogenemia has been found, which has a detrimental effect on oocyte quality and therefore contributes to lower fertilization rates." (PMID 34122349, 2021). "Due to the higher prevalence of Hashimoto’s Thyroiditis (HT) in Polycystic Ovary Syndrome (PCOS) patients, we aimed to evaluate ovarian reserve and the effect of autoimmune exposure time on ovarian reserve in PCOS patients with HT by Anti-Müllerian hormone (AMH) levels." (PMID 33750377, 2021). "In GCs of polycystic ovary syndrome (PCOS), FSH might inhibit the excessive secretion of AMH by suppressing its promoter activity." (PMID 31623192, 2019). "With a further increase in the AMH levels, the inhibition of FSH activity becomes more prominent and may cause anovulation in women, especially in those with polycystic ovary syndrome (PCOS)." (PMID 30427868, 2018). "LH strengthens this effect, because when granulosa cells are cultured with LH, the expression of AMH is up-regulated in anovulatory polycystic ovaries, which is not observed in normal ovaries." (PMID 30153296, 2018). "Does Anti-Mullerian Hormone reflect antral follicle count similarly in women with or without polycystic ovary syndrome or polycystic ovarian morphology?" (PMID 26799212, 2016). "The screening criteria for age-related anti-Müllerian hormone (AMH) and polycystic ovary syndrome (PCOS) have significant implications for Chinese women of childbearing age." (PMID 40597965, 2025). "Accordingly, AMH has been proposed as a marker of polycystic ovary syndrome and a substitute for AFC in diagnosing PCOS, especially when the ultrasound criteria remain controversial." (PMID 34830389, 2021). "The aim of this study was to investigate the expression of anti-Mullerian hormone (AMH), kisspeptin 1 (KISS-1), and kisspeptin 1 receptor (KISS1r) in rat models of polycystic ovary syndrome (PCOS) and controlled ovarian stimulation (COS)." (PMID 31782699, 2020). "Finally, marking the excess of antral follicles in women with polycystic ovary syndrome (PCOS), AMH assay may soon replace and/or complete the ultrasound ovarian morphology criterion in the diagnosis of this syndrome." (PMID 33013710, 2020). "Increased Anti-Mullerian Hormone in polycystic ovary syndrome, may be due to overactive follicles rather than reflect antral follicle count." (PMID 26799212, 2016). "The authors suggested that in adolescents for whom vaginal scans are not feasible or in patients without hyperandrogenemia, AMH may be used as a surrogate parameter in the diagnosis of PCOS, superior to androgens and gonadotropins." (PMID 28913069, 2015). "Unlike FSH, the luteinizing hormone (LH) does not alter AMH expression in the GCs of healthy women or normo-ovulatory patients with polycystic ovary syndrome (PCOS), but increases AMH in the GCs of PCOS individuals with chronic anovulation." (PMID 41515619, 2026). "Conversely, no AMH cut-off could distinguish polycystic ovaries from GCTs." (PMID 41515619, 2026). "In women without polycystic ovary syndrome (PCOS), serum AMH levels and antral follicle count were significantly lower in women with short cycles and higher in women with oligo/amenorrhea than those with a normal menstrual cycle." (PMID 34177795, 2021). "Therefore, serum levels of AMH are proportional to the number of developing antral follicles in the ovaries and may represent both the quantity and quality of the ovarian follicle pool.A number of studies have shown serum AMH levels to be increased in women with polycystic ovary syndrome (PCOS)." (PMID 23904873, 2013).
polycystic ovary syndrome (continued). "Yilmaz and colleagues investigate the FF AMH levels of non-obese non-hyperandrogenemic PCOS, excluding the possible effect of hyperandrogenemia on AMH levels." (PMID 37493841, 2023). "No biochemical signs of hyperandrogenemia or FSH, LH, AMH and E2 dysregulation in other patients were detected." (PMID 34751898, 2022).
endometriosis (74 papers, 2011 to 2026). The growth of functional endometrial tissue in anatomic sites outside the uterine body. "Bilateral endometriosis is more correlated with deep infiltrating endometriosis, potentially complicating surgical management and elevating the risk of postoperative complications, including a decrease of anti-Müllerian hormone(AMH)." (PMID 41030271, 2025). "Another retrospective study comparing single-port, robot-assisted laparoscopy versus single-port laparoscopy found the former approach linked to higher AMH values after the procedure; however, this was only the case for cases of stage I/II endometriosis." (PMID 40507534, 2025). "In univariate and multivariate linear regression analyses, age, ovarian cyst size, location of cyst, complexity of surgery, and the severity of endometriosis were associated with the reduction in AMH levels after surgery." (PMID 37510787, 2023). "Age, ovarian cyst size, location of cyst, complexity of surgery, and the severity of endometriosis were associated with the reduction in AMH levels after surgery." (PMID 37510787, 2023). "REM analysis of all 10 sets of data (n = 1099) showed that GnRH-a pretreatment (7 days to 6 cycles) can cause dynamic changes in serum AMH levels in endometriosis patients." (PMID 35698127, 2022). "Despite similar levels of serum AMH between the groups, fewer oocytes in women withinfertility associated with endometriosis were retrieved than in patients in thecontrol group (p<0.001)." (PMID 36350241, 2022). "Our findings strongly suggest that urinary MnBP was associated with endometriosis, and MnBP can affect gene expression and attenuate the ratio of the mitochondrial membrane potential, AMH, and inhibin B production in human granulosa cells." (PMID 32151056, 2020). "This suggests a faster decline of the number of primordial follicles associated with a faster decrease of AMH levels, and thus a direct effect of endometriosis on ovarian reserve." (PMID 28791295, 2017). "Ovarian cystectomy of endometriosis lesions has been associated with significant decrease in ovarian reserve assessed by measurement of serum AMH level in previous studies; especially when bipolar cauterization has been administered during the procedure." (PMID 26000005, 2015). "It is well-known that endometriosis is associated with low AMH." (PMID 37959232, 2023). "Taking into account that the size of endometrioma is associated with significant post-operative decreases in AMH levels and that endometriosis is a progressive disease, early detection and conservative management might prevent future reproductive problems." (PMID 34755503, 2022). "Endometriosis, by contrast, is associated with lower ovarian reserve, increased primordial follicle recruitment, fewer antral follicles, and a steeper rate of decline in AMH." (PMID 34295358, 2021). "In conclusion, the concentration of AMH in PF correlates with age and serum AMH levels, but these associations may be less relevant in women with endometriosis." (PMID 33263001, 2020). "And further analysis of the impact of previous ovarian surgery on ovarian reserve in patients with different endometriosis staging, as well as the association between the change of serum AMH and benign ovarian diseases other than endometriosis will be further elucidated in the future." (PMID 26359251, 2015). "When we compared the AMH reduction rates according to these risk factors, the decrease in ovarian function was more severe in patients with old age, bilateral endometrioma, severe endometriosis (advanced stage, AAGL stage III/IV), complex surgeries, and large ovarian cysts (p < 0.05)." (PMID 37510787, 2023). "The observed reduction in follicle numbers, increased apoptosis, and downregulation of critical factors such as AMH and KL highlight the multifaceted mechanisms by which endometriosis impairs ovarian function." (PMID 40002761, 2025).
endometriosis (continued). "The evidence on the impact of surgery for extra-ovarian localizations of endometriosis on the AMH values is limited." (PMID 40507534, 2025). "The precise clinical significance of AMH levels, in terms of predicting the probability of pregnancy after endometriosis surgery, is an interesting topic that, however, needs to be further investigated." (PMID 40507534, 2025). "Endometriosis decreased AMH protein expression (p < 0.05 vs. Sham), although no significant changes were seen in KITLG (KL mRNA) or GDF-9 expression." (PMID 40002761, 2025). "Women with endometriosis generally exhibit lower levels of AMH and antral follicle count and elevated levels of follicle-stimulating hormone compared with those without endometriosis or healthy controls." (PMID 40304605, 2025). "Future research on AMH in endometriosis should prioritize high-quality, long-term, prospective studies with standardized assays and appropriate control groups to enhance comparability and clinical relevance." (PMID 40507534, 2025). "Regarding the effect of endometriosis surgery on AMH values, the majority of the published literature focuses on patients with OMA, raising concerns regarding a potentially harmful effect of surgery on the ovarian reserve." (PMID 40507534, 2025). "In fact, womenwho received ultra-long GnRH protocol had larger uterine volumes and insome studies a higher rate of dismenorrea (Geet al., 2023) or confirmed endometriosis, andeven lower AMH levels compared with long GnRHa protocol." (PMID 40674550, 2025). "In this narrative review, we critically present the available evidence regarding the impact of different endometriosis phenotypes, as well as the effect of endometriosis surgery, on AMH levels." (PMID 40507534, 2025). "Further research should focus on the extra-ovarian locations of endometriosis and their impact on AMH values." (PMID 40507534, 2025). "All patients in our study underwent minimally invasive surgery for endometriosis, and most of them had a postoperative AMH value between 1–2 ng/mL (36%) or below 1 ng/mL (32%)." (PMID 39044926, 2024). "Endometriosis is associated with reduced AFC and AMH, suggesting a reduction in ovarian reserve, especially in those with ovarian endometrioma and advanced stage." (PMID 38800489, 2024). "This can be attributed to lower AFC and AMH values in endometriosis patients, which is a result from endometriosis (advanced stages and/or endometrioma) itself and from surgery." (PMID 37123402, 2023). "IL6 represents for some authors a useful marker for endometriosis and AMH is considered as an important indicator of oocyte quality and follicle selection." (PMID 36902616, 2023). "In women with endometriosis, reduced ovarian reserve is manifested by a significant decrease in oocyte count and AMH levels." (PMID 37560165, 2023). "An altered hormonal environment was also reported in the follicular fluid of endometriosis patients with a decrease in concentrations of estradiol (E2) and AMH." (PMID 36902616, 2023). "Another strength of this study is that it compared the serial changes in AMH levels after endometriosis surgery between the robot group and the laparoscopy group for a relatively large number of patients." (PMID 37510787, 2023). "In our analysis, similar to previous studies, the decrease in AMH levels was greater with increasing age, cyst size, and severity of endometriosis." (PMID 37510787, 2023). "It is known that patients with endometriosis have lower AMH levels at baseline than those with other benign ovarian tumors or healthy women due to the disease-induced chronic inflammatory response and immune modulation." (PMID 37510787, 2023). "A recent systematic review has concluded that the presence of endometriosis significantly decreases AMH levels when compared to controls." (PMID 37959232, 2023).